CD81 (CD81 molecule)
Diseases named in the same sentence as CD81 in open-access papers (continued):
Sharing a sentence is not in itself a finding about the gene and the disease.
infection (continued). "P. yoelii sporozoites strictly require CD81 for infection, and can invade Hepa1-6 cells and HepG2/CD81 cells, but not the parental HepG2 cells that do not express CD81." (PMID 29975762, 2018). "The S29 cells only support HCV RNA replication, virus particle assembly, and release but not infection, since the Huh7-derived S29 cells were deficient for HCV entry receptor CD81, thus it is suitable for a single-cycle production assay." (PMID 30564209, 2018). "The HepG2/CD81 infection rate was not altered after siEphA2, as compared to the control, but was dramatically reduced after siCD81, as expected." (PMID 29975762, 2018). "Expectedly, Lunet N cells lacking CD81 were refractory to infection with HCV and with lentiviruses pseudotyped with HCV glycoproteins, which rely on HCV receptor interaction during entry." (PMID 30024968, 2018). "Although these clones (clones 15, 23, 46, 67 and 111) exhibited a high affinity to the antigenic peptide (data not shown), they hardly prevented HCVcc (cell cultured HCV) infection of Huh7.5.1 monolayers compared with those treated with anti-CD81 mAb." (PMID 29682171, 2018). "Four cell-surface molecules, CD81, occludin (OCLN), claudin 1 (CLDN1), and scavenger receptor class B member 1 (SRB1), are particularly important for HCV cell entry, although only CD81 and OCLN determine the species-specificity of infection." (PMID 29765366, 2018). "Lunet N cells lacking detectable CD81 expression served as negative control in all infection and proteomics experiments." (PMID 30024968, 2018). "In contrast with Hepa1-6 cells, the human hepatocarcinoma HepG2 cells express SR-BI but not CD81, and as a consequence support infection by P. berghei but not P. yoelii sporozoites." (PMID 29975762, 2018). "The downregulation of CD81 was found to be bi-phasic and did not require viral gene expression early in infection." (PMID 29121670, 2017). "At later time points of infection, however, continued downregulation of CD81 required expression of IE and E, but not L genes." (PMID 29121670, 2017). "Remarkably, complementation of PbΔp52/p36 with PyP52 and PyP36 restored infection in HepG2/CD81 but not in HepG2 cells, where only low numbers of UIS4-negative intranuclear EEFs were observed." (PMID 28506360, 2017). "In sharp contrast, a mouse mAb specific for SR-BI greatly reduced infection, with no additive effect of anti-CD81 antibodies." (PMID 28506360, 2017). "Accordingly, HCVpp-E1-E2 (SB strain) infection of Raji cells was inhibited by anti-B7.2 and anti-CD81/anti-SR-BI (known HCV co-receptors), but not by a control isotype antibody." (PMID 28067225, 2017). "Although the HCV polymerase inhibitor 2’CMA and CD81 specific antibodies efficiently blocked Jc1 infection, none of the protein or antibody treatments greatly affect infection with this virus." (PMID 27115873, 2016). "Untreated HepG2 cells, which do not express CD81 and are thus less permissive to infection with JFH-1, were used as a negative control." (PMID 27280294, 2016). "Lack of CD81 did not preclude infection of HC-04, and endogenous expression of CD81 on THLE-2 and -3 was not sufficient to allow for efficient infection." (PMID 26070149, 2015). "Analysis of DENV RNA in the cells treated with anti-CD81, however, revealed that this receptor was not essential for B cell infection." (PMID 26656738, 2015). "Infection of human cell lines and primary hepatocytes can be blocked by specific antibodies directed against CLDN1 and kinetics of inhibition with such antibodies showed that CLDN1 acts cooperatively with CD81 and SR-BI in HCV entry." (PMID 24509809, 2014). "HCV can enter macrophages through non-CD81 mediated phagocytic uptake that is independent of productive infection." (PMID 23633957, 2013). "Absence of CD81 on hepatocytes merely prevents productive infections but it does not alter the capacity of sporozoites to traverse hepatocytes." (PMID 23255300, 2013).
infection (continued). "Among the host factors reported to influence the virus life cycle in vitro and in vivo, CD81 was the first reported receptor to be involved in the in vitro infection process, and CD81 was also necessary in our HCV-RMT infection system because infection was blocked by anti-CD81 mAb." (PMID 24358200, 2013). "Lentiviral expression of an shRNA targeting OCLN in HepG2+miR-122+CD81 cells efficiently silenced expression of endogenous OCLN and impaired infection with both HCVpp and HCVcc bearing the glycoproteins from the H77 genotype 1a and HC-J6 2a isolates, respectively." (PMID 23555257, 2013). "Ten days after infection, the supernatant from HDAdJFH1-infected Huh-7 cells was found to be infectious and the infectivity of HCV could be inhibited by anti-E2 and anti-CD81 antibodies in a dose-dependent manner." (PMID 23987099, 2013). "Naïve HepG2 cells do not express CD81; however, complementation with exogenous CD81 (HepG2-CD81) induces susceptibility to HCV infection, although the level of infection in these cells is 724-fold reduced compared to Huh-7.5 cells." (PMID 23056952, 2012). "Several studies have shown that siRNA against CD81 distinctly inhibited HCV entry (> 90%) in HCV serum infection irrespective of HCV genotype, viral load, or liver donor." (PMID 21896165, 2011). "In vitro, non-permissive human, mouse, and hamster cell lines become permissive to infection with HCV pseudoparticles (HCVpp) if engineered for ectopic expression of SR-BI, CD81, CLDN1, and occludin suggesting these are the core HCV receptors required for entry of the virus into hepatocytes." (PMID 20838466, 2010). "Unlike Jc1/mCD81, Jc1/G451R still displays a strong preference for infection via human rather than mouse CD81." (PMID 20617177, 2010). "By using cell lines that expressed little or no CD81 and that were refractive to infection with cell-free virus, we showed that the occurrence of viral cell-to-cell transmission is not influenced by the levels of CD81 on either donor or recipient cells." (PMID 19088272, 2009). "The cells were washed and fresh media, without anti-CD81, was added and the efficiency of HCVcc infection was compared to a control infection." (PMID 19643019, 2009). "Infection was also not detected upon infection of Huh7-Lunet cells that express low amounts of CD81 (not shown)." (PMID 19521536, 2009). "CD81 is essential for the infection of hepatocytic cells not only by several Plasmodium species, but also by the hepatitis C virus." (PMID 18389082, 2008). "A mAb that requires this region for optimal binding did not block infection, in contrast to other CD81 mAbs." (PMID 18389082, 2008). "This is not the case since the only mAb (5A6) that requires this critical site for maximum binding does not block infection, in contrast to all other CD81 mAbs." (PMID 18389082, 2008). "Moreover, the expression of CD81 in human liver-derived cells, HepG2 and HH29, that were previously resistant to infection conferred permissiveness to HCV pseudotype infection." (PMID 15836798, 2005). "Moreover, PCV2 infection reinforced the interaction between CD81 and Syndecan-1, suggesting that PCV2 may utilize this interaction to promote its own infection." (PMID 39745447, 2025). "This revealed, as expected, that infectious Jc1_mScarlet-2A was not able to spread in CD81-negative Huh7.5 cells (left) whereas non-infectious Jc1_NS5A-mScarlet and Jc1_E2-mScarlet failed to induce spreading infection in both, control as well as CD81KO Huh7.5, confirming their loss of infectivity." (PMID 38357447, 2024). "The patients in the study, whether CD81 positive or negative, had other clinical complications such as infection and bleeding, and the rates were not too different among the two groups." (PMID 37309539, 2023). "Furthermore, because CD81 represents a multi-pathogen receptor (for HCV, HIV, Plasmodium, Mab), targeting this receptor deserves thorough attention, as a large part of the human population is exposed to these infections." (PMID 36818301, 2023).
infection (continued). "In addition, related human pathogenic alphaviruses, including SFV, SINV, Ross River virus (RRV) and Venezuelan equine encephalitis virus (VEEV) but not coronaviruses, require CD81 for efficient infection." (PMID 35612284, 2022). "However, HIV-1 entry and infection can also be inhibited by tetraspanin protein blockages, such as CD9 and CD81, and CD81-mediated inhibition of viral entry could indicate the specificity of exosomes in different cell types." (PMID 33348699, 2020). "In the absence of infection CD81 is thought to regulate migration of liver cells." (PMID 30024968, 2018). "Although 67-2 minimally but significantly prevented VSVpp infection, the relative luminescence unit (RLU) was not significantly different from that in cells exposed to anti-CD81 mAb, supporting that the inhibitory effect of the mAb 67-2 on HCVpv and HCVpp is not due to variations in infection rates." (PMID 29682171, 2018). "However, the four peptides did not interact with HCV receptors (SRB1, claundin-1, CD81 and occludin), consistent with the lack of antiviral activity of these four peptides when incubated with the cells before infection." (PMID 28638089, 2017). "In conclusion, these data show downregulation of CD9, CD81, CD151, and EGFR upon infection with two herpesviruses, two orthopoxviruses and a negative strand RNA virus, suggesting that the reduction of cell surface expression of these molecules is common upon infection." (PMID 29121670, 2017). "To better establish the link between the infection of HLMF by HCV and profibrotic properties, we compared the relative expression of a-SMA, and collagens I and IV mRNAs in cells infected with either HCVcc or UV-inactivated HCVcc, and in HCVcc-infected cells treated with anti-CD81." (PMID 26214688, 2015). "Thus, Cd81−/− mice inoculated i.v. with 106 infectious PyWT failed to develop a blood stage infection (5000 PyWT is the minimum dose to obtain 100% blood stage infection in BALB/c mice)." (PMID 23255300, 2013). "The observation that CD81ΔC diffuses slower than wild-type and supports reduced HCVpp infection of non-polarized HepG2 cells suggests that CD81 lateral diffusion speed may limit HCV internalization." (PMID 23126643, 2013). "Finally, we show that HCV J6-derived glycoproteins adapted to mouse CD81 permit infection of mouse cells in the absence of human factors." (PMID 20617177, 2010). "Cell-to-cell spread of HCV differs from infection with cell-free virus in that it is refractory to neutralization by HCV E2 monoclonal antibodies and occurs in a CD81-independent manner, thus representing an alternative mode of transmission that may be important in vivo." (PMID 20838466, 2010). "CD81 has subsequently proven critical for entry based on the absence of infection from lack of surface expression, either naturally or through gene silencing, and by inhibition of entry using blocking antibodies or peptide competitors derived from the LEL region." (PMID 21994703, 2010). "Moreover, the selected aptamers, especially ZE2, could competitively inhibit E2 protein binding to CD81, an important HCV receptor, and significantly block HCV cell culture (HCVcc) infection of human hepatocytes (Huh7.5.1) in vitro." (PMID 19997645, 2009). "This may suggest that this region of CD81, although not essential, contributes to the function of CD81 during infection." (PMID 18389082, 2008). "Our initial data, using CD9×81 and CD9LEL81 chimeras, indicated that CD81 SEL could be replaced with that of CD9 without affecting the ability to support P. yoelii sporozoites infection." (PMID 18389082, 2008). "Because only this subset of CD81 molecules would play a role in the infection by Plasmodium sporozoites, this model explains why 5A6, which is the only mAb that requires CD81 A–B region for binding is also the only mAb that fails to inhibit P. yoelii and P. falciparum sporozoite infection." (PMID 18389082, 2008).
infection (continued). "Indeed, the reciprocal chimera CD81ccg9 supported P. yoelii sporozoite infection after transient transfection in HepG2-A16 cells, showing that CD81 A and B helices in a CD9 backbone are sufficient to confer HepG2-A16 cells the ability to support infection by P. yoelii sporozoites." (PMID 18389082, 2008). "Indeed, it was shown that the binding of E2 to CD81 was not predictive of an infection-producing interaction between HCV and host cells." (PMID 15836798, 2005). "Furthermore, HepG2 cells expressing a C-terminal truncated CD81 mutant supported comparable levels of HCV entry independent of polarization status, suggesting that membrane protein dynamics on polarized cells may limit pathogen attachment and infection." (PMID 27983476, 2017). "Using 1D6, we could demonstrate that these two chimeras were expressed at a level similar to that of CD81 in transfected HepG2-A16 cells (data not shown), indicating that the lack of infection after transfection of these chimeras is not due to diminished surface expression." (PMID 18389082, 2008). "The fact that the level of infection obtained after transfection of CD81ccg9 was repeatedly lower than after CD81 transfection, suggested that in addition to the A-B region, the second half of CD81 LEL (comprising the C, D and E helices) may contribute to CD81 function during Plasmodium infection." (PMID 18389082, 2008). "In contrast, infection of other enveloped RNA viruses such as the arenavirus Junin virus (JUNV; Candid #1) or human coronavirus 229E (CoV-229E) did not depend on CD81 at any of the MOIs tested." (PMID 35612284, 2022). "The ability of viral spread for both genomes was widely dependent on the presence of CD81 as the co-culture with Huh7-Lunet CD81N cells, lacking CD81 expression, resulted in the absence of infection events in case of GLT1-20M." (PMID 35763545, 2022). "Knocking-down OCLN in virus-prone T cell line inhibited HCV infection, while de novo infection downregulated OCLN and CD81, and upregulated CD5 without modifying SR-B1 expression." (PMID 23626783, 2013). "Indeed, the ability of anti-CD81 mAb QV-6A8-F2-C4 to block cell-cell transmission and dissemination post-infection without any detectable toxicity suggests that targeting CD81 may also hold promise for the treatment of chronic infection in combination with other antivirals." (PMID 23704981, 2013). "Since this effect was maintained in cells that lack endogenous levels of CD81, a crucial cell entry factor for HCV, we can rule out that this effect was due to increased virus production and secondary rounds of infection." (PMID 22558311, 2012). "All cell lines were equally permissive for VSVGpp infection (8 × 105-9 × 105 RLU, data not shown) however, only Huh7, Hep3B, PLC and HepG2 cells stably expressing CD81 (HepG2-CD81) were permissive for HCVpp infection." (PMID 22273112, 2012). "Human CD81-expressing IPK17 cells were infected with full-length JFH1FL, however, no infection was detected (data not shown)." (PMID 21731692, 2011). "Although both CD81 and SRBI are needed for a productive HCVpp infection, there was a lack of synergy when blocking both receptors which points to a lack of cooperativity between the two receptors in a HCVpp infection." (PMID 19643019, 2009). "Expression of CD81 enhances CHIKV permissiveness, while a lack of CD81 decreases infection." (PMID 35612284, 2022). "This differential effect of HCV infection on the expression of CD81, OCLN and CD5, but not SR-B1 gene, provided supporting evidence that the respective proteins might be engaged in the infection process induced by HCV in T cells." (PMID 23626783, 2013).
cancer (121 papers, 2010 to 2026). A tumor composed of atypical neoplastic, often pleomorphic cells that invade other tissues. "Cluster of differentiation (CD) markers such as CD79b, CD45, CD23, CD22 and CD81 serve as reliable prognostic indicators in CLL as well as the human leukocyte antigen (HLA) with its well-documented associations with various cancers." (PMID 39329950, 2024). "Remarkably, only the CD9 fused RFP was correctly managed by 5637 cancer cells, whereas transfection with CD81 variant resulted in a series of possible degradation products." (PMID 36579638, 2023). "Closely related members of the Tspan8 subfamily, including CD9, CD81 and Tspan8, are associated with cancer and metastasis." (PMID 36078095, 2022). "As a pleiotropic protein, CD81 could be a profitable target to interrupt complex cellular processes, implicated in multigenic diseases such as cancers." (PMID 37046846, 2023). "Interestingly, CD9 has been successfully engineered to load cytosolic proteins or enzymes into EVs, while CD81 has also been mutated to gain the cancer-targeting ability for potential anticancer therapy." (PMID 36559058, 2022). "Consequently, CD81 has been implicated in cancer progression." (PMID 40604335, 2025). "In the NC group, haematoxylin–eosin (HE) staining revealed residual vacuoles formed by adipose tissues and the infiltration of cancer cells into the omentum, and knocking down CD81 expression improved these phenomena." (PMID 40604335, 2025). "Herein, we provided a comprehensive illustration of the integrated cell–cell crosstalk between cancer cells and Tim4+ TAMs regulated by CD81." (PMID 40604335, 2025). "Recent studies have highlighted the key role of CD81 in promoting cancer stemness and metastasis by interacting with CD44, a cell surface adhesion receptor which is highly expressed in many cancers." (PMID 40411659, 2025). "The expression of Ki67 was increased in the NC group, which showed greater proliferation of cancer cells compared to the sh‐CD81 group." (PMID 40604335, 2025). "We found that the amount of the EpCAM-positive EVs (also CD81-positive) or the CD24-positive EVs increased as the cancer progressed from Stage II to III." (PMID 39513819, 2024). "Our investigation revealed that the exosome‐dominated EV subpopulation (Exo), captured using a combination of CD63/CD9/CD81 antibodies, proved effective as an mRNA‐based cancer marker." (PMID 38204202, 2024). "Through SDS-PAGE analysis, we discovered that the ratio of CD63 to CD81 in different EVs is consistent and distinct, making it a reliable characteristic for recognizing EVs secreted by cancer cells." (PMID 39194595, 2024). "In cancer, exosomes have been shown to carry specific proteins, such as CD63 and CD81, that are often upregulated in cancer cells, as well as specific miRNAs and mRNAs that can be used to monitor disease progression and treatment response." (PMID 38845750, 2024). "We confirmed an increase in cytotoxicity against target cancer cells when CD81 and CD82 were overexpressed in the T cells." (PMID 38515751, 2024). "The amount of EpCAM-positive EVs (also CD81-positive) increased from 18% to 29% as the cancer progressed from Stage II to III." (PMID 39513819, 2024). "To explore the impact of T-cell activation and cytokine expression on cancer cell cytolysis, particularly that influenced by CD81 and CD82, as observed in our preceding results, we embarked on a series of investigations." (PMID 38515751, 2024). "Their application can be diverse, but at present anti-CD81 have been essentially considered for the treatment of cancer." (PMID 37046846, 2023). "Here, we screened peptides that bind to the tetraspanin CD81 protein, and evaluated their inhibitory activity in cancer cell migration." (PMID 36979448, 2023). "Our vision is essentially cancer-oriented, but the analysis shall serve to identify and design CD81 binders applicable in other therapeutic domains as well." (PMID 37046846, 2023).